INS (insulin)
Diseases named in the same sentence as INS in open-access papers (continued):
Sharing a sentence is not in itself a finding about the gene and the disease.
Insulin resistance (continued). "Moreover, there is a physiologic increase in plasma insulin and insulin resistance in puberty, which extends to adolescence in the presence of overweight/obesity." (PMID 38289144, 2024). "Whereas with the Rotterdam study, the effects of insulin and insulin resistance were seen only in the first three years, when the recruited subjects were followed-up 9.7 years after the study, a possible role in advancing the onset of Alzheimer’s dementia was concluded." (PMID 39518747, 2024). "Our findings suggest that highly oxidative and insulin-sensitive type I muscle fibers are decreased in PCOS which in combination with more extra-myocellular lipids may be key factors for insulin resistance in PCOS muscle." (PMID 38180081, 2024). "In a functional magnetic resonance (MRI) study, women with PCOS showed a decreased amplitude of low-frequency fluctuation, associated with poor executive performance and depressive disorders, and this negatively correlated with the plasma insulin level in subjects with insulin resistance." (PMID 38256230, 2024). "Furthermore, the interaction between insulin and the vascular, renal, and nervous systems indicates the pivotal roles of hyperinsulinemia and insulin resistance in hypertension." (PMID 38892574, 2024). "Although transient increases in [Ca2+]i induced by insulin can stimulate glucose uptake in target tissues, a chronic and aberrant elevation of [Ca2+]i can have a significant impairment for insulin-dependent glucose uptake and the context of insulin resistance." (PMID 39594636, 2024). "Chronic inflammation might promote the occurrence of T2D by increasing insulin resistance, affecting insulin signaling, and promoting beta-cell dysfunction." (PMID 38427644, 2024). "A possible explanation is that patients using external insulin might already have higher insulin resistance limiting the effectiveness of semaglutide in those patients." (PMID 39205685, 2024). "Insulin resistance and impaired insulin action in adipose tissue is a key defect in the development of the metabolic syndrome and has been found to precede other metabolic abnormalities seen with obesity, often developing rapidly in mouse models following exposure to WD." (PMID 38961153, 2024). "Insulin resistance improves the plasma levels of insulin and glucose, further promoting DNL." (PMID 39229376, 2024). "Elevated blood insulin before early AD may contribute to both AD pathology and insulin resistance, although human data is limited." (PMID 38534454, 2024). "The compensatory insulin secretion and hyperinsulinemia that would follow our hypothesis for insulin resistance fit nicely into the well-established concept of a hyperbolic relationship between insulin secretion and insulin sensitivity." (PMID 40604313, 2024). "Previous studies have indicated that in metabolically healthy individuals, insulin has a vasodilatory effect on microvasculature, whereas in the presence of insulin resistance and metabolic syndrome, insulin is reported to have a mainly vasoconstrictive effect on the microvasculature." (PMID 39661465, 2024). "High GI foods potentially lead to a rapid increase in blood glucose and insulin levels, which may contribute to insulin resistance, inflammation, and oxidative stress, all of which are associated with kidney dysfunction." (PMID 39143076, 2024). "Insulin resistance leads to elevated insulin and insulin-like growth factor 1 (IGF-1), which is an effective growth stimulator and may induce scleral tissue growth and elongation of the eye axis, thus leading to the development of myopia." (PMID 38191303, 2024). "Quercetin can also modulate hyperglycemia and insulin levels, improving insulin resistance." (PMID 38892574, 2024). "As could already be suspected from the fasting insulin level scores, a statistically significant (p = 0.04) relationship was found between the presence of insulin resistance (measured using the HOMA-IR index) and sperm motility." (PMID 38792339, 2024).
Insulin resistance (continued). "Moreover, adiponectin from adipose tissue inhibits insulin resistance, reduces hepatic steatosis, and has anti-inflammatory, anti-apoptotic, and insulin-sensitizing effects in NAFLD." (PMID 38310315, 2024). "Improvements in insulin sensitivity and glucose metabolism, which are pivotal in metabolic syndrome, showing that improving insulin resistance and metabolic abnormalities could offer protective effects against AD." (PMID 39246604, 2024). "Still, AKR1C3 expression has also been observed to be induced by insulin and insulin resistance, and it has been proposed that insulin may upregulate androgen biosynthesis, including 11-oxygenated androgens." (PMID 38498076, 2024). "However, as the disease progresses, the pancreatic beta cells’ ability to secrete sufficient insulin to compensate for the insulin resistance is impaired." (PMID 38999858, 2024). "High insulin levels may indicate developing insulin resistance in cells and an increase in hyperinsulinemia." (PMID 38929138, 2024). "TNFα is also involved in inducing insulin resistance; thus, a potential decrease of TNFα signaling by the decrease of inflammatory pathways seen in pigs supplemented with milk might benefit insulin sensitivity." (PMID 39705291, 2024). "Insulin resistance describes a state where the effect of a given concentration of insulin is reduced; this may become more important in feedlot cattle as cattle are harvested at increasingly greater fatness." (PMID 38828800, 2024). "However, no clear association emerged between TN and glycated hemoglobin, serum insulin levels, and homeostasis model assessment of insulin resistance (HOMA-IR)." (PMID 37702926, 2024). "Firstly, insulin resistance can lead to increased production of reactive oxygen species (ROS), which in turn exacerbates insulin resistance through various mechanisms, including impaired insulin signaling and inflammation." (PMID 39229375, 2024). "Fat accumulation in obesity leads to insulin resistance, which increases insulin secretion." (PMID 39050759, 2024). "This study indicated that aminoadipic acid levels are elevated in liver of FGF21 KO mice, also supporting the hypothesis that increased insulin secretion and insulin resistance exist in FGF21 KO mice." (PMID 38653921, 2024). "As the improvement of insulin resistance usually concurs with the decrease in pancreatic insulin production, insulin may also play a role in inhibiting the hepatic production of SHBG." (PMID 38238336, 2024). "In insulin resistance, these physiological actions of insulin are impaired." (PMID 39610878, 2024). "Elevated serum α- and β-glucose in PAG may indicate that GHD induced insulin resistance with reduced peripheral insulin sensitivity." (PMID 38611940, 2024). "However, it is well-established that inflammation induces insulin resistance, which leads to an increased co-secretion of insulin and IAPP." (PMID 39062913, 2024). "Therefore, a new concept has been proposed: a chronically elevated insulin level (hyperinsulinemia) is the main driver of insulin resistance." (PMID 39769002, 2024). "Studies have shown that ceramides directly affect insulin signaling, leading to insulin resistance." (PMID 39695759, 2024). "In addition, it has been reported that butyrate can improve insulin sensitivity and prevent insulin resistance in mouse models and large population cohorts." (PMID 38998662, 2024). "Firstly, the release of inflammatory cytokines may result in insulin resistance, disrupting insulin signaling and affecting glucose metabolism and lipid accumulation, promoting fat deposition and obesity development." (PMID 39720251, 2024). "Moreover, the fasting serum insulin level was increased and the homeostasis model assessment of insulin resistance (HOMA-IR) showed an increase in shAdgra3 mice." (PMID 39718208, 2024).
Insulin resistance (continued). "Interventional studies have suggested that supplementation of zinc, selenium, and chromium might improve insulin resistance by reducing oxidative stress which can impair insulin secretion from β cells." (PMID 38310135, 2024). "Moreover, insulin resistance increases, which prevents insulin from exerting its full impact, and increases TG levels." (PMID 38731722, 2024). "The analysis revealed a significant and positive association between FABP4 and HbA1c (r = 0.126, p < 0.001), fasting blood glucose (FBG) (r = 0.184, p < 0.001), fasting insulin (r = 0.326, p < 0.001), and the homeostatic model of insulin resistance (HOMA-IR) (r = 0.333, p < 0.001)." (PMID 38731797, 2024). "Women with insulin resistance may have lower ovarian reserve, reduced oocyte quality, and decreased embryo implantation rates compared to non-insulin-resistant individuals." (PMID 39767708, 2024). "When insulin resistance occurs in the brain, a reduced amount of insulin transported by the BBB causes a relative insulin deficiency and the inability of the insulin signaling pathway, which ultimately impairs central and peripheral metabolic function, possibly affecting mood and cognition." (PMID 39767690, 2024). "Since skeletal muscle is influential in insulin-mediated glucose metabolism, developing sarcopenia may induce insulin resistance." (PMID 38996156, 2024). "According to previous studies, continuous exogenous insulin treatment induces the production of insulin antibodies and increases insulin resistance, which may have increased insulin requirements." (PMID 38686463, 2024). "In an effort to identify novel insulin resistance genes, we focused our attention on loci that had not previously been associated with insulin resistance and metabolic diseases." (PMID 39277575, 2024). "On the other hand, probiotic intake was specifically associated with varying effects on insulin levels and insulin resistance, including reductions, increases, and no significant changes." (PMID 39796486, 2024). "The elevation in circulating insulin that often accompanies insulin resistance could thereby exacerbate insulin signaling responses in the female reproductive system." (PMID 38131197, 2024). "Moreover, deacyl gymnemic acid treatment dramatically reduces insulin resistance and systolic blood pressure and enhances glycemic and lipid profiles as well as insulin sensitivity in a murine model of MetS." (PMID 39125340, 2024). "However, in some women, this normal increase in insulin resistance overburdens their pancreatic B-cells, which cannot adequately boost insulin secretion." (PMID 39770967, 2024). "Insulin resistance and impaired insulin secretion contribute to this dysregulation." (PMID 38421266, 2024). "Furthermore, a detrimental feedback loop exists between insulin function and age-related decline, worsening insulin resistance." (PMID 39588187, 2024). "Measurements of insulin resistance such as fasting glucose (5.5 ± 0.5 vs 4.3 ± 0.3 mmol/L, P = .0006), insulin (11.9 ± 3.3 vs 5.8 ± 2.2 mU/L, P = .0032), HOMA-IR (2.9 ± 0.8 vs 1.1 ± 0.4, P = .0009), and NEFAs (465 ± 191 vs 240 ± 83 μM, P = .0251) were substantially greater in the obese group." (PMID 38917410, 2024). "In conclusion, our findings suggest that combining DCHD with conventional treatment for NAFLD offers advantages over conventional treatment alone, leading to improved liver function, regulated lipid metabolism, reduced insulin resistance, modulated insulin function, and decreased BMI." (PMID 39015790, 2024). "Peripheral insulin resistance, a hallmark feature of PCOS, is characterized by a dual impairment involving diminished insulin action in response to glucose overload and elevated basal insulin secretion." (PMID 39594244, 2024). "Subjects with either T2DM or prediabetes exhibit myocardial insulin resistance, but it is still unsettled whether sex-related differences in myocardial insulin resistance occur in diabetic and prediabetic subjects." (PMID 38671460, 2024).
Insulin resistance (continued). "It has been suggested that insulin resistance and high insulin levels increase IRAP activity and alter AVP turnover, which leads to increased synthesis of vasopressin, and may play a role in the development of metabolic syndrome." (PMID 39769071, 2024). "Furthermore, JNK activation significantly compromises insulin signal transduction, resulting in diminished tissue sensitivity to insulin as well as the emergence of insulin resistance." (PMID 38904034, 2024). "Therefore, to maintain blood sugar values within the normal range, the pancreas must secrete more significant amounts of insulin, resulting in hyperinsulinemia (increased circulating insulin levels), an essential characteristic of insulin resistance." (PMID 39061991, 2024). "It is the result of insulin resistance and subsequent inhibition of the insulin signaling pathway." (PMID 39683552, 2024). "There were no other significant associations of baseline values or changes in any other body composition variables (including liver and muscle fat fractions) with changes in indices of insulin sensitivity/insulin resistance or insulin secretion/beta cell function." (PMID 39152223, 2024). "In addition, bST also increased blood concentrations of insulin, as it promotes an increase in glucose concentrations and insulin resistance." (PMID 38612336, 2024). "However, when insulin sensitivity in peripheral tissues is compromised, the hypoglycemic effect of insulin is diminished, giving rise to insulin resistance and hyperinsulinemia." (PMID 39519550, 2024). "Moreover, GLP-2 receptor activation has been shown to prevent the glucose dysregulation that occurs following the induction of insulin resistance by prolonged high-fat feeding in mice, partly through enhancing insulin signalling." (PMID 39766228, 2024). "Insulin resistance is connected to impairment in insulin signaling, and the compensatory overactivation of insulin signaling pathways may increase the secretion of Aβ and the hyperphosphorylation of tau." (PMID 37980298, 2024). "While insulin resistance is linked to obesity and type 2 diabetes, even though they are insulin resistant, the majority of obese individuals do not experience hyperglycemia." (PMID 39104999, 2024). "Hyperinsulinemia, characterized by insulin resistance or aggressive insulin treatment, might directly contribute to immune cell impairment, which is a key factor in the onset of PE48,49." (PMID 39521940, 2024). "Furthermore, a systematic review and meta-analysis of randomized clinical trials investigating vitamin D supplementation combined with calcium showed positive effects on insulin, insulin resistance, and blood glucose." (PMID 38812030, 2024). "Insulin resistance arises in part due to dysfunctional insulin signaling." (PMID 38807790, 2024). "Consequently, enhancing glucose uptake in skeletal muscles and augmenting insulin sensitivity within these muscles emerge as significant strategies for the prevention or mitigation of insulin resistance, hyperglycemia, and type 2 diabetes." (PMID 39095777, 2024). "It is characterised by persistently elevated blood glucose occurring as a result of peripheral insulin resistance and reduced insulin production which may lead to multiple long-term health conditions such as retinopathy, neuropathy, and nephropathy." (PMID 39911238, 2024). "Insulin resistance results in elevated plasma glucose and insulin levels." (PMID 39411175, 2024). "Additionally, the PI3K/AKT pathway is reported to regulate insulin and hyperglycemia, and the insulin resistance and the AGE-RAGE axis can activate PI3K/AKT signaling." (PMID 38241313, 2024). "Psychological insulin resistance was assessed by the scale of My Opinion on Insulin (MOI)." (PMID 39036047, 2024). "Insulin resistance in skeletal muscle decreases glycogen synthesis in the muscle, and increases hepatic de novo lipogenesis and triglyceride synthesis, resulting in atherosclerotic dyslipidemia in lean insulin resistant people." (PMID 39411175, 2024).
Insulin resistance (continued). "The proposed mechanisms for the role of 25-hydroxyvitamin D in improving insulin resistance in obesity include reducing inflammation, enhancing peripheral and hepatic glucose uptake, and regulating insulin synthesis and secretion by pancreatic β cells through direct and indirect pathways." (PMID 38836246, 2024). "Another hypothesis is that chronic inflammation can lead to the accumulation of ROS, which can promote insulin resistance by impairing insulin signaling and damaging cellular structures." (PMID 39435991, 2024). "Since hepatic Zbtb18 deletion predisposes HFD-fed mice to serious glucose intolerance and insulin resistance, it is easy to take it as an indication that Zbtb18 plays a predominant role in alleviating the HFD-induced dysfunctional glucose and insulin responses." (PMID 38263084, 2024). "However, most insulin-dependent antidiabetic drugs induce hyperinsulinemia and increase insulin resistance and glucotoxicity." (PMID 38304078, 2024). "DM is marked by insulin resistance, where cells become less responsive to insulin." (PMID 39347125, 2024). "It is important to know that anticancer treatment could either induce insulin resistance or deplete insulin production by producing islet cell antibodies." (PMID 39522614, 2024). "These processes may contribute to the development of insulin resistance and damage to insulin-sensitive tissues." (PMID 38669382, 2024). "A higher HOMA-IR score suggests more severe insulin resistance and reduced insulin sensitivity." (PMID 39765819, 2024). "In addition, it is well known that aerobic exercise can improve insulin resistance by increasing insulin signaling proteins such as GLUT4 and GLUT4 vesicle-associated protein." (PMID 38671435, 2024). "We also generated a proxy for severity of insulin resistance during pregnancy based on insulin treatment, yet arguably, the proxy may rather represent beta-cell dysfunction or a combination of the two." (PMID 39497166, 2024). "Furthermore, fasting insulin concentration and Homeostatic Model Assessment for Insulin Resistance (HOMA‐IR) were decreased similarly in both groups (fasting insulin: 1 [−9, 11] pmol∙L−1; HOMA‐IR: 0.1 [−0.3, 0.5] AU; both p ≥ 0.617)." (PMID 39358836, 2024). "Since the over-production of pro-inflammatory cytokines and oxidative stress has been attributed to insulin resistance and type-2 diabetes, probiotics might have a beneficial effect on improving insulin sensitivity by reducing systemic inflammation." (PMID 38729941, 2024). "However, the role of insulin in regulating lipid metabolism and improving insulin resistance in peripartum obese dairy cows remains contentious." (PMID 39881718, 2024). "Insulin resistance is a condition in which the body produces insulin but cannot use it properly." (PMID 38254596, 2024). "In addition, some reports have established a correlation between glaucoma and type 2 diabetes, characterized by the inability of cells to effectively respond to insulin, also known as insulin resistance." (PMID 39110798, 2024). "PTEN is a negative regulator of insulin signaling and its activation may promote insulin resistance." (PMID 39411175, 2024). "This promotes insulin resistance and disrupts insulin signaling pathways." (PMID 39431546, 2024). "Bacteroidetes was found to be enriched in the gut of insulin-sensitive individuals, and it reduced fecal monosaccharide accumulation, resulting in lowered lipid accumulation and inflammation, which contributes to reduced insulin resistance." (PMID 39451562, 2024). "This decrease may be clinically relevant in lowering insulin resistance and improving insulin sensitivity in the young population." (PMID 38173399, 2024). "The improvement in FMD could also be influenced by insulin sensitivity, a link between insulin resistance and endothelial dysfunction well known." (PMID 39595161, 2024).